IL6 (interleukin 6)
Diseases named in the same sentence as IL6 in open-access papers (continued):
Sharing a sentence is not in itself a finding about the gene and the disease.
atherosclerosis (continued). "Sleep fragmentation also increases inflammatory markers (IL-1, IL-6, IL-17, CRP and TNF-α) and triggers a low-grade chronic inflammatory status, hereby increasing atherosclerosis risk and severity, even independently of other atherosclerotic risk factors." (PMID 34440753, 2021). "Cytokines involved in human atherosclerosis can be broadly classified as pro-inflammatory and pro-atherogenic (such as IL-1, IL-6, and TNF) or as anti-inflammatory and anti-atherogenic (such as IL-10 and IL-1rA)." (PMID 34076144, 2021). "This cytokine has been shown to be responsible for initiating the atherosclerosis process in rodents with diminished activity of apolipoprotein E. The association between adhesion molecules, TNF-α and IL-6 is common in ESRD, promoting atherosclerosis." (PMID 34441451, 2021). "As atherosclerosis is considered a chronic inflammatory disease, inhibiting the expression of proinflammatory cytokines such as interleukin-6 (IL-6) and IL-1β is another potential treatment strategy." (PMID 33875621, 2021). "In our experiments, in AEC only IL-6 synthesis was increased, and the consequence of that effect can be the acceleration of atherosclerosis." (PMID 33641611, 2021). "The salicylate drug Salsalate has been shown to significantly reduce several inflammatory markers including IL-6 and TNFα, and ameliorate mechanisms involved in atherosclerosis in vitro." (PMID 33626069, 2021). "Proinflammatory cytokine IL-6 is a proatherogenic cytokine, and sustained IL-6 production promotes the development of atherosclerosis." (PMID 34539804, 2021). "IL-6 promotes the proliferation of vascular smooth muscle tissue, an early component of hypertension and atherosclerosis." (PMID 33924229, 2021). "Other factors triggering age-related atherosclerosis include the vasculature and myeloid cells of the immune system which activate the inflammatory pathways, especially IL-6." (PMID 34072794, 2021). "IL-1 signaling leads to the expression of secondary inflammatory cytokines such as IL-6; therefore, IL-1 is a critical factor in the process of atherosclerosis." (PMID 34071276, 2021). "The effects induced by IL-6 are associated with cardiovascular diseases; several studies have already reported IL-6 alterations in such diseases and atherosclerosis." (PMID 33935717, 2021). "At the same time, interleukin 6 (IL-6) and tumor necrosis factor-alpha (TNF-α) increase and are linked to the development of cardiovascular disease, atherosclerosis, and others." (PMID 34072421, 2021). "D-dimer can activate monocytes to secrete pro-inflammatory cytokines such as interleukin-6 (IL-6), which play an important role in endothelial dysfunction, atherosclerosis and promotion of hypercoagulability." (PMID 33773590, 2021). "Atherosclerosis is a chronic inflammatory disease and recent study indicated that atherosclerosis‐related inflammation is mainly mediated by pro‐inflammatory cytokines (IL‐1β, IL‐6 and TNF‐α) and inflammatory signaling pathways (Gisterå & Hansson, 2017)." (PMID 34592792, 2021). "A team has found that OSA and hypertension have an interactive effect on the progression of carotid atherosclerosis and the level of inflammatory markers of atherosclerosis in the blood (such as interleukin-6 and pentapeptidase-3)." (PMID 35058810, 2021). "In another study, milk-derived tripeptides decrease proinflammatory cytokines IL-1β, IL-6 as well as SOCS3 in the abdominal aorta of ApoE-deficient mice, thus reducing atherosclerosis development." (PMID 33801489, 2021). "Compared with the SAT, the expression of the IL-6 gene in extremely severe atherosclerosis was increased by 1.7 times in the PVAT and by 2.5 times in the EAT." (PMID 33735200, 2021). "Studies have confirmed that the long-term activation of the IL-6 signaling pathway is significantly related to the degree of atherosclerosis in elderly patients." (PMID 34957238, 2021).
atherosclerosis (continued). "We have investigated the presence of IL6 signaling in advanced manifest atherosclerosis in BiKE, a Swedish cohort of patients in Stockholm undergoing CEA due to carotid artery stenosis." (PMID 33350884, 2021). "D-dimers enhance the inflammatory mediators such as IL-1, IL-6, and their levels also increase during process of atherosclerosis." (PMID 34221279, 2021). "IL-6 is known to be involved in the inflammatory processes of atherosclerosis, potentially by its involvement in the acute phase responses of tissue injury and in chronic inflammation where an elevation of the Il-6 level is seen." (PMID 33868439, 2021). "Given the pathogenic role of proinflammatory cytokines in AIRD-related atherosclerosis, tight control of disease activity with biologic DMARDs, including TNF-α inhibitors, IL-6 inhibitors, and IL-17 inhibitors, may reduce the risk of ASCVD." (PMID 34066436, 2021). "It would seem that an increase in the levels of inflammatory cytokines, such as interleukin 6, the Creactive protein and the tumor necrosis factor a, compromise endothelial functioning, promoting the process of atherosclerosis." (PMID 34356253, 2021). "IL-6 is a predictive biomarker of atherosclerosis as it contributes to the generation of atherosclerosis through metabolic, pro-coagulant, and endothelial mechanisms." (PMID 34360333, 2021). "The pro-inflammatory cytokines tumour necrosis factor alpha (TNF-α) and interleukin-6 (IL-6), which are involved in the pathogenesis of RA, are predictive of subsequent CV events, as both play important roles in atherosclerosis." (PMID 33259776, 2021). "HR (95% CIs) of clinical outcomes according to atherosclerosis vascular beds involvement numbers and IL-6 level in patients with AIS or TIA at 1 year follow-up." (PMID 33927687, 2021). "IL-1β and IL-6 are the predominant pro-inflammatory ILs in atherosclerosis mainly by aggravating subsequent inflammatory cascades, mediating the acute-phase response, and promoting the fatty streak formation in atherogenesis." (PMID 33413490, 2021). "NETs turn on the transcription of IL-6 and pro-IL-1β genes in macrophages during the early inflammatory stages of atherosclerosis." (PMID 34827513, 2021). "The Multi-Ethnic Study of Atherosclerosis revealed that higher IL-6 and CRP concentrations indicate a faster declining rate of kidney function." (PMID 32877465, 2020). "IL-6 was related to atherosclerosis, and high circulating IL-6 levels contributed to foam cell formation in atherosclerotic lesions." (PMID 33029103, 2020). "In turn, IL-6 induces oxidative stress and endothelial dysfunction through overexpression of angiotensin II type 1 receptor in the atherosclerosis process." (PMID 32566106, 2020). "Upon infiltration, macrophages are activated by OxLDL and subsequently secrete inflammatory cytokines, such as TNF-α and IL-6, enhancing the progression of atherosclerosis." (PMID 32752134, 2020). "Cytokines play a key role in inflammatory diseases and a link with hypercholesterolemia and atherosclerosis has emerged mainly for the IL-6, IL-1, and TNFα pathways." (PMID 32849284, 2020). "In experimental atherosclerosis, IL-6 mRNA expression was found in the atherosclerotic plaques of apoE−/− mice." (PMID 32194407, 2020). "The only serum biomarker that differed in patients depending on the presence of 70% stenosis was IL-6, which, on the opposite, was elevated in patients with less severe atherosclerosis." (PMID 33854919, 2020). "Primary proinflammatory cytokines produced by macrophages during atherosclerosis initiation and development are IL-1β, IL-6, TNFα, and CCL2." (PMID 33374145, 2020). "Considering the vital role of IL‐6 in atherosclerosis, the mechanism responsible for producing IL‐6 is a pivotal question." (PMID 32374489, 2020).
atherosclerosis (continued). "We and others have demonstrated that in mouse models of atherosclerosis, perioperative stress leads to a systemic inflammatory reaction resulting in a rapid, interleukin-6 (IL-6)-dependent, expansion of plaque volume and increase in plaque vulnerability." (PMID 32133374, 2020). "In animal models, dietary supplemented POA decreased the expression of pro-inflammatory cytokines TNF-α and IL-6 and reduced atherosclerosis development." (PMID 33348748, 2020). "In contrast to this, in a state of established atherosclerosis (atherosclerotic plaques), miR-342-5p has been described to induce pro-inflammatory mediators including nitric oxide synthase 2 (Nos2) and IL-6." (PMID 33003647, 2020). "The status of DNA methylation is lower in transcriptionally active genes, and our results are consistent with the concept that methylation is important in controlling the expression of IL-6 as seen in atherosclerosis." (PMID 33123328, 2020). "The aim of the present study is the examination of IL6 mRNA Levels and hypomethylation of IL6 promoter in atherosclerosis patients." (PMID 33123328, 2020). "Chronic supplementation of rice bran enzymatic extract also ameliorates atherosclerosis-related oxidative stress and inflammation markers such as interleukine-6 (Il6) and tumor necrosis factor α (Tnfa) mRNA expressions." (PMID 32806520, 2020). "As a pro‐inflammatory and immune‐regulatory cytokine, IL‐6 plays an important role in the genesis and maintenance of the inflammatory response in atherosclerosis." (PMID 32374489, 2020). "The studies of animal models of atherosclerosis demonstrated a marked increase of IL-6 synthesis in response to dietary cholesterol intake." (PMID 32587660, 2020). "So far, HDAC9 has been reported to affect several aspects of the pathogenesis of atherosclerosis, i.e. cholesterol efflux, platelet aggregation, interleukin 6 (IL-6) signaling, macrophage function, inflammation progression and vascular calcification." (PMID 32284067, 2020). "Previous studies showed that a reduction in the secretion of IL-6 and IL-17 reduced the formation of Th17 cells, the degree of atherosclerosis, and the production of proteinuria." (PMID 32724324, 2020). "The cytokines contributing to atherosclerosis can be broadly divided into proatherogenic (such as IL-1β, IL-6, TNF-α) and antiatherogenic (such as IL-10 and IL-1rA)." (PMID 32485823, 2020). "In this case, inflammatory cells and activated endothelial cells in atherosclerotic plaques upregulate adhesion molecules and release inflammatory cytokines such as tumor necrosis factor-α (TNF-α), IL-6, and IL-1β, promoting the progression of atherosclerosis." (PMID 33330454, 2020). "PDCD4 is involved in atherosclerosis pathology probably through enhancing levels of IL-6 and IL-8 and promoting apoptosis of VSMC in animal models of coronary atherosclerosis." (PMID 32599769, 2020). "In fact, interleukin-6 (IL-6) and C-reactive protein (CRP) are key inflammatory biomarkers associated with an increased risk of atherosclerosis and cardiovascular disease." (PMID 32210181, 2020). "Several studies indicated that IL-6 has critical pathophysiological roles in cardiovascular diseases, such as atherosclerosis." (PMID 32516877, 2020). "High circulating IL-6 levels contributed to foam cell formation in atherosclerotic lesions and were one crucial step in the pathobiology of atherosclerosis." (PMID 33029103, 2020). "Both IL-6 and IL-8 are well-established mediators of RA-related atherosclerosis, and we found that CD11c expression was positively correlated with increasing levels of IL-6 and IL-8." (PMID 32824307, 2020). "Our study reported a significant increase in IL-6 gene expression in whole blood in patients with atherosclerosis than controls." (PMID 33123328, 2020). "Several studies showed that interleukin-6 (IL-6) is involved in the pathogenesis of atherosclerosis." (PMID 33123328, 2020).
atherosclerosis (continued). "IL-6 is released from activated leukocytes in response to infection or trauma and from vascular smooth muscle cells in response to atherosclerosis." (PMID 32823680, 2020). "Inflammation is regarded to play an important role in the etiology and progression of atherosclerosis, and both interleukin 6 (IL-6) and monocyte chemoattractant protein 1 (MCP-1) seem to be associated with this process." (PMID 32221618, 2020). "The chronically high concentration of pro-inflammatory cytokines like IL6 and TNFα found in atherosclerosis and T2D attenuates renal and vascular Klotho expression by increasing FGF23 concentration through the NF-κB pathway." (PMID 33322009, 2020). "Macrophages and their secreted cytokines IL-1β and IL-6 play a significant role in promoting atherosclerosis." (PMID 32384892, 2020). "Accompanied by enhanced levels of IL-1β and IL-6, a deficiency of macrophage scavenger receptor class B type I (SR-BI) and macrophage LRP-1 increases cell death and inflammation in atherosclerosis." (PMID 32346605, 2020). "Interleukin-6 (IL-6) is an important stimulator of atherosclerotic lesions, which can aggravate atherosclerosis." (PMID 32509885, 2020). "There is currently evidence that IL-6 plays an important role in propagating the inflammatory response that is responsible for atherosclerosis." (PMID 31583485, 2020). "In recent years, interesting studies explored the role of IL-1 signal pathway in the progression of atherosclerosis due to its direct effect on the synthesis of different inflammatory cytokines, including IL-6 and CRP." (PMID 31110500, 2019). "Endothelial senescence is currently emerging as a contributor to the pathogenesis of atherosclerosis by increasing ROS production, decreasing NO availability, and increasing the production of pro-inflammatory molecules IL-6, IL-1, IL-8, CCL2, and ICAM-1." (PMID 30377700, 2019). "Expression of IL-6 is regulated by IL-6 receptor and signal transducing protein gp130; IL-6 being a pro-atherogenic cytokine exacerbates the progression of atherosclerosis in ApoE-/- mice." (PMID 32082145, 2019). "Early experimental data implicating IL-6 in atherosclerosis demonstrated that exogenous injection of IL-6 into hyperlipidaemic mice significantly increased atherosclerotic lesion size." (PMID 31357404, 2019). "Given the role of IL-6 in atherosclerosis, investigators have begun to examine the impact of IL-6 blockade in cardiovascular disease." (PMID 30873416, 2019). "PAF is involved in the induction of many pro-inflammatory and growth factors; among them, interleukin-6 (IL-6) is one of the most interesting, in view of its role in atherosclerosis." (PMID 31289638, 2019). "Our results suggest that ROS-mediated IL-6 signaling will be a valuable therapeutic target to prevent vanadium air pollution-mediated inappropriate smooth muscle cell function and atherosclerosis." (PMID 31817202, 2019). "Incubation of the mentioned cell cultures with CPB promoted the release of IL-6, a pro-inflammatory cytokine engaged in the development of atherosclerosis." (PMID 31731607, 2019). "By the administration of probiotic VSL#3, interesting modulations on host metabolism have been described, such as the modest reduction of IL1, TNF-α, and IL6, the main responsible cytokines of the inflammatory atherosclerosis." (PMID 31205450, 2019). "IL-6 is also a major contributor to the development of atherosclerosis by playing a dual pathological and protective role." (PMID 31616435, 2019). "The linear random effect model allowed us to pinpoint other possible effects of DNT5 (adipose tissue expression of Il6, Il1β, Ccl2, atherosclerosis in the artic conduit, hepatic expression of Srebp1c and Acaca)." (PMID 30692584, 2019). "We provide evidence that the oxidizing vanadium salts, VOSO4 and NaVO3, promote VSMC synthetic differentiation, migration, and proliferation and consequent atherosclerosis via ROS-mediated IL-6 induction." (PMID 31817202, 2019).
atherosclerosis (continued). "MSCs isolated from atherosclerosis patients secrete high levels of IL-6, IL-8, and MCP-1, leading to a reduced immunomodulatory capacity." (PMID 31885770, 2019). "The uncontrolled TNF-α and IL-6 production lead to metabolic disorders such as type 2 diabetes and atherosclerosis." (PMID 30909606, 2019). "Recently, several clinical studies on atherosclerosis have suggested that IL-6 seems to be a potential marker for atherosclerosis." (PMID 31292433, 2019). "Free fatty acids (FFAs), high-sensitivity C-reactive protein (hs-CRP), adiponectin (APN), insulin (INS), and interleukin-6 (IL-6) can induce atherosclerosis through arterial inflammation." (PMID 31191115, 2019). "The present study investigated the involvement of Chlamydia trachomatis and Chlamydia pneumoniae infections and immunological markers (C-reactive protein, CRP, TNF-α, IL-6, IL-8, and IL-10) in the process of atherosclerosis." (PMID 30804931, 2019). "The identified genes were enriched by pathways such as atherosclerosis, IL-6, IL-9, IL-8, growth hormone, and JAK/STAT signalling pathways." (PMID 31205673, 2019). "The reduction of atherosclerosis by CLO and TIC was associated with lower serum IL-6 levels and less MΦ infiltration to the atherosclerotic intima." (PMID 31242230, 2019). "For example, increased TNF-α expression is associated with the deterioration of renal function in uremia and IL-6 is related to the promotion of muscle wasting and atherosclerosis." (PMID 30795639, 2019). "IL-1 and IL-6 both are suggested to contribute to atherosclerosis, with the former (along with other cytokines) likely stimulating production of the latter in endothelial cells." (PMID 30373222, 2018). "IH‐induced increases in IL‐6 levels point to a potential role for IL‐6 in IH‐induced progression of atherosclerosis." (PMID 29744301, 2018). "Pro-inflammatory cytokines, such as IL-1, TNF-α, C-reactive protein (CRP), IL-2, and IL-6, all increase in patients with atherosclerosis." (PMID 30386532, 2018). "The contribution of IL-6 to the pivotal role of inflammation shared by psoriasis and atherosclerosis is crucial." (PMID 29535705, 2018). "Numerous clinical trials using anti-IL-6 antibodies or antibodies directed against the IL-6 receptor (IL-6R) have shown therapeutic significance of blocking IL-6 signaling in chronic inflammatory diseases, including atherosclerosis." (PMID 30185178, 2018). "Independently of traditional cardiovascular factors, higher plasma concentrations of IL-6 and expression of chemokine coreceptor CCR5 on monocytes were associated with atherosclerosis." (PMID 29666424, 2018). "Inflammatory mediators, such as IL-6 and IL-8, are crucial to the pathophysiology of atherosclerosis." (PMID 29875665, 2018). "In the Multi-ethnic Study of Atherosclerosis (MESA) study, continuous strong, positive associations between GGT and CRP, interleukin-6 (IL-6), and soluble intercellular adhesion molecule-1 (sICAM-1) were observed in multivariable models." (PMID 29491346, 2018). "IL-6 is an important upstream inflammatory cytokine in propagating the downstream inflammatory response for atherosclerosis." (PMID 29875665, 2018). "Acute phase response, mediated by pro-inflammatory cytokines like CRP, IL-6 and IL-8, in its chronic state, leads to chronic disorders including atherosclerosis and cardiovascular events." (PMID 29439738, 2018). "In atherosclerosis model mice, the IL-6 and TNF-α level were significantly increased in plasma and aortic tissues when p-STAT3 levels were increased." (PMID 30142970, 2018). "Several inflammatory cytokines, such as TNF-α, IL-1β and IL-6, have been shown to induce VSMCs proliferation/migration and hypertrophic response, which can contribute to the development of atherosclerosis." (PMID 29728095, 2018). "The detection of inflammatory biomarkers such as CRP and adhesion molecules IL-6 and MMPs can be a good means of diagnosing atherosclerosis and cardiovascular disease." (PMID 30142970, 2018).